GRK2 (G protein-coupled receptor kinase 2)
Diseases named in the same sentence as GRK2 in open-access papers (continued):
Sharing a sentence is not in itself a finding about the gene and the disease.
tumor (continued). "Immunohistochemistry staining (IHS) showed that the expressions of GRK2 and GRK3 were significantly lower in tumor than in adjacent tissues, correlated with disease-free survival and overall survival (OS) in HCC patients, while the GRK6 might mediate a tumor growth signaling." (PMID 35769816, 2022). "In this regard, the G protein-coupled receptor kinase 2 (GRK2) can act as regulator of both G protein-coupled receptors (GPCRs), including CXCR4/ACKR3, and GFR of the receptor tyrosine kinase (RTKs) family, and has emerged as a critical signaling hub involved in orchestrating most tumor hallmarks." (PMID 36233192, 2022). "We unravel that chronic adrenergic stimulation triggers the upregulation of both GRK2 and HuR protein levels, increases cytoplasmic HuR and fosters nuclear HIF-1α presence, thus, mimicking a pseudo-hypoxia situation that might contribute to tumor progression." (PMID 32413989, 2020). "Furthermore, restoration of GRK2 expression level significantly rescued the hyperproliferative phenotype, colony formation and migration capacities of the eIF3d knockdown NOZ cells, although it does not fully restored tumor malignancy as compared with the control group." (PMID 28594409, 2017).
cancer (24 papers, 2011 to 2025). A tumor composed of atypical neoplastic, often pleomorphic cells that invade other tissues. "The presence of GRK2–HDAC6 complexes at the leading edges of migrating HeLa cells is associated with increased GRK2-mediated cell motility and cancer metastasis." (PMID 39941046, 2025). "Certain signaling pathways instrumental in many cancers cause the upregulation of GRK2 protein levels in malignant cell lines." (PMID 23691268, 2013). "However, in pathologies associated with upregulated GRK2, such as cardiovascular, renal, metabolic, cancer, and neurodegenerative diseases, enhanced receptor desensitization is not always desirable." (PMID 36275707, 2022). "Our results point out that centrosome and spindle alterations could be a novel pro-tumoral effect of GRK2 instructed by both gain and loss of protein kinase levels in different types of cancer." (PMID 33806062, 2021). "GRK2 plays a role in the molecular pathophysiology of various cancers by regulating various molecular processes." (PMID 40224487, 2025). "This approach can potentially advance the treatment of autoimmune conditions and cancer, highlighting the importance of further research into GRK2′s role in immune regulation and disease pathogenesis." (PMID 40224487, 2025). "A multidisciplinary approach that integrates molecular biology, pharmacology, and clinical research will be essential to fully elucidate GRK2′s contributions to immune dysregulation and cancer progression." (PMID 40224487, 2025). "GRK2 reduces cell proliferation in thyroid cancer, suggesting a possible inhibitory role in some cancer types." (PMID 40224487, 2025). "As malignant tumor growth rely on increased bioenergetic demand, the impact of GRK2 on IGF1R signaling warrants further inverstigation as it holds pharmacological promise to various cancer types." (PMID 35430346, 2022). "GRK2 its tightly regulated and altered GRK2 levels and activity are reported in pathological contexts, such as metabolic dysfunctions and several types of cancer." (PMID 33806062, 2021). "In sum, our data put forward a relevant role for the GRK2/HuR/HIF1α module in cancer cells and in response to the adrenergic overdrive, regardless of the oxygen status." (PMID 32413989, 2020). "In this context, we previously demonstrated that GRK2 directly affects mitochondrial function, therefore, we cannot exclude a direct mitochondrial effect of GRK2 in cancer." (PMID 33256128, 2020). "From the small number of reports on the role of GRK2 in cancer cells it emerges that the effects vary and depend on the cancer type, promoting growth and survival in some and inhibiting it in others." (PMID 31554835, 2019).
cancer (continued). "RKIP directly inhibits key cancer-promoting kinases such as GRK2, Rac, and GSK3β, and these kinases can regulate MYCN expression through Raf-independent mechanisms." (PMID 28187004, 2017). "RKIP can also inhibit G-protein coupled receptor kinase-2 (GRK2), which activates a number of cancer-critical pathways and broadly regulates ligand-receptor signaling through clathrin-dependent endocytosis (CDE)." (PMID 28187004, 2017). "In this regard, it is important to note the importance of GRK2 on ET-1 receptors, downstream events, and its relationship with cancer." (PMID 23691268, 2013). "The importance of the strong immunologic relationship to most cancers is illustrated in part by high expression of GRK2 in different cellular types of the immune system." (PMID 23691268, 2013). "However, in breast cancer and other cancer types, GRK2 promotes growth factor signaling and cell proliferation, suggesting a possible promotional role in these cancers." (PMID 40224487, 2025). "A thorough understanding of GRK2 may position it as a potent therapeutic target in treating inflammation and cancer." (PMID 40224487, 2025). "Furthermore, emerging research has expanded our understanding of GRK2′s involvement in cancer biology." (PMID 40224487, 2025). "Furthermore, GRK2′s involvement in cancer biology is underscored by its capacity to modulate tumorigenesis, metastasis, and angiogenesis through intricate signaling networks." (PMID 40224487, 2025). "Altered GRK2 expression has been observed in many human cancers and may play a role in angiogenesis." (PMID 37686662, 2023). "Serine 153 phosphorylation (pSer153-RKIP) by protein kinase C ζ (PKCζ) has been found in some cancer types to account for the loss of RKIP activity that in turn activates MAP kinase pathway and inhibit GPCR through inhibition of G protein-coupled receptor kinase 2 (GRK2)." (PMID 36291854, 2022). "However, dysregulated GRK2 levels and enhanced desensitization are the main drivers of pathology involved in cardiovascular, renal, metabolic, cancer, and neurodegenerative diseases." (PMID 36275707, 2022). "Moreover, inhibition of GRK2 enhanced degradation of cancer-relevant insulin-like growth factor-1 receptor (IGF1R) and prevented its interaction with recruited β-arrestin 2, restraining malignant cell growth." (PMID 35430346, 2022). "Emerging evidence indicates that GRK2 acts as an onco-modulator, influencing multiple cellular functions related to the hallmarks of cancer, such as cell proliferation, cell survival, cell motility, cell metabolism, and angiogenesis, via its impact on cancer-relevant signaling networks." (PMID 33546162, 2021). "It is worthy of note that both types of GRK2 dysfunction are frequent in several cancer types." (PMID 33806062, 2021). "Indeed, in the past decades, the GRK2 interactome was greatly explored and novel substrates have been identified that can participate in cancer progression." (PMID 33256128, 2020). "Third, UCA1 overexpression could promote cancer metastasis by activation of metastasis-related genes including GRK2/ERK-MMP9, EZH2/AKT, p21/E-cadherin, iASPP, KLF4-KRT6/13, FGFR1/ERK and ZEB1/2-FSCN1." (PMID 30918102, 2019). "Some of us and others have also found a critical role of GRK2 in the endothelin signaling cascade and many of the effects of ET-1 on cancer may be mediated by GRK2." (PMID 23691268, 2013).
cancer (continued). "Furthermore, within the cancer microvascular environment, the endothelial-specific downregulation of GRK2 appears to promote the recruitment of macrophages to cancer sites directly through altered chemotactic secretion and indirectly through the promotion of leaky blood vessels." (PMID 40224487, 2025). "Besides inducing the angiogenic remodeling of tumoral stroma, GRK2-induced pseudo-hypoxia might favor cancer cell de-differentiation and emergence of cancer stem-like cells." (PMID 32413989, 2020). "Recent studies indicate that GRK2 interacts with PI3K, Akt, and MEK, implicating its involvement in inflammation, cardiovascular disease (CVD), and cancer therapeutics." (PMID 40224487, 2025). "Recent studies have shown that TNF-α stimulates FLS; TNF-α receptor 2 transactivates GRK2 via TRAF2, promoting desensitization of EP4 receptors, which leads to cancer-like proliferation of FLS and contributes to disease progression in RA." (PMID 40224487, 2025). "Stimulation of GRK2 upon hypoxia or adrenergic receptor activation emerges as a novel mechanism of regulation of HIF signaling in physiological or pathological processes, such as cancer progression." (PMID 32413989, 2020). "Interestingly, nerve growth factor (NGF) in combination with GRK2 promotes opioid receptors phosphorylation whilst amplifying the pain, and when treated with anti-NGF therapies, there was significant relief in cancer bone pain by mediating the outcome of GRK2 and arrestins." (PMID 33806057, 2021). "Furthermore, the possibility to pharmacologically inhibit GRK2 to delay cancer cell proliferation has never been explored." (PMID 33256128, 2020). "It is known that altered GRK2 expression levels modulate chemokines-mediated induction of MEK/ERK activity through both kinase-dependent and -independent function and its aberrant epithelial cell motility that plays a key role in cancer progression and metastasis." (PMID 23691268, 2013).
infection (20 papers, 2008 to 2025). The state of being infected such as from the introduction of a foreign agent such as serum, vaccine, antigenic substance or organism. "Prior research from our lab has shown that GRK2 is required for JCPyV internalization and infection, and the knockdown of GRK2 using siRNA reduces β-arrestin coupling to the 5-HT2Rs." (PMID 39459893, 2024). "The G protein-coupled receptor kinase 2 (GRK2) is also required for infection, presumably by initiating β-arrestin recruitment to the receptor." (PMID 39459893, 2024). "Addition of the inhibitor during the first 3 h of infection was sufficient to reduce viral production by more than 1000-fold, confirming the requirement for GRK2 activity during the early steps of the viral cycle." (PMID 30206219, 2018). "In these cases, the inhibition of viral replication was clearly observed at 4 h post-infection (hpi), suggesting that, as predicted by our phosphoproteomic data, both CDKs and GRK2 are required for an early step in the viral replication cycle." (PMID 30206219, 2018). "In summary, our work reveals the unique phosphorylation signature induced by IAV within minutes of infection and identifies GRK2 as lead target for host cell-directed antivirals." (PMID 30206219, 2018). "To verify this, we performed a time of addition experiment in which the GRK2 inhibitor (GRK2i) was added to cells at different times post-infection." (PMID 30206219, 2018). "In the GRK2−/− MEFs, the infection was decreased by 7.8 to 19.8 fold at a M.O.I. of 1 and 5, respectively, compared to the infection in GRK2−/−, bGRK2 cells." (PMID 23029581, 2012). "YFV-17D infection in GRK2−/− MEFs was compared to infection in GRK2−/−, bGRK2 MEFs which stably express bovine GRK2 in a GRK2−/− background." (PMID 23029581, 2012). "In the GRK2−/− MEFs the infection was decreased by 28 to 33 fold compared to the infection in the GRK2−/−, bGRK2." (PMID 23029581, 2012). "Lentiviral infection is used to introduce small hairpin RNAs to interfere with the translation of the key signaling proteins GRK2, Gαi2, Gαq, PLCβ3 and PLCβ4." (PMID 18818727, 2008). "Decrease of infection observed upon reduction of GRK2 expression may be due to an alteration of virus entry, viral RNA translation, viral RNA synthesis, and/or infectious particle assembly and release." (PMID 23029581, 2012). "To investigate whether GRK2 also plays a role in later stages of infection we used DENV replicons expressing renilla luciferase (Rluc) in place of the structural proteins." (PMID 23029581, 2012). "Notable genes in the resistant phenotype included the protein tyrosine kinase src and protein kinase D, with 14-3-3 protein, G-protein coupled receptor kinase 2, twitchin, titin and nuclear factor κB (NFκB) inhibitor differentially expressed only following infection." (PMID 23300533, 2012). "Moreover, numerous Ser/Thr kinases (STKs) were either increased (e.g., GRK2, ROCK2, ROCK1, PAK1) or decreased (e.g., BMP2K, TNIK, MYLK, and NRBP1) in expression in the patient samples, suggesting a widespread change in the kinome caused by pathogen infection." (PMID 38389037, 2024). "As a GRK2 inhibitor, it was hypothesized that treatment with paroxetine would prevent the recruitment of β-arrestin to the receptor, which is critical for JCPyV-receptor mediated endocytosis and infection." (PMID 39459893, 2024). "Importantly, we also observed the appearance of the phosphorylated form of GRK2 upon IAV infection confirming our hypothesis that GRK2 is phosphorylated within minutes of infection." (PMID 30206219, 2018). "Finally, we tested whether chemical inhibition of GRK2 could reduce viral replication and severity of infection in mice." (PMID 30206219, 2018). "IL-33 prevents the TLR signaling-mediated induction of G protein-coupled receptor kinase-2 (GRK2) and maintains the expression of the chemokine receptor CXCR2, allowing neutrophils to migrate to the site of infection for bacterial clearance." (PMID 38082335, 2023).
infection (continued). "In the absence of GRK2, the phosphorylation level of p38MAPK and p47phox was augmented following H37Rv infection; this effect was also induced by the GRK2 inhibitor in a dose-dependent manner." (PMID 36000734, 2022). "One contributing factor is thought to be TLR-induced upregulation of G protein-coupled receptor kinase 2 (GRK2) expression, which ultimately desensitizes neutrophils to CXCL2 coming from the site of infection, thereby inhibiting several functions as well as their migration." (PMID 34795676, 2021). "Although in vivo inhibition of GRK2 using paroxetine led to a significant reduction in upper respiratory tract viral load and to a modest reduction in lower respiratory tract titers at 4 days post infection, this inhibition was not protective from lethal infections." (PMID 31031778, 2019). "G-protein coupled receptor kinase 2 (GRK2) is a potential pro-viral host protein for influenza A virus and is inhibited by paroxetine acting as virion un-coating can reduce viral load in respiratory tracts but is not helpful in lethal infection prevention." (PMID 32665783, 2020). "At the highest M.O.I. of 10, low level of infection could be detected in the GRK2−/− cells, indicating that GRK2 was not absolutely essential for infection but was required for robust infection in MEFs." (PMID 23029581, 2012).
heart disease (9 papers, 2011 to 2025). "MDM2’s Influence on GRK2 Activity: MDM2 has been shown to regulate cardiac contractility by inhibiting GRK2-mediated desensitization of β-adrenergic receptors, highlighting its potential as a therapeutic target in heart diseases." (PMID 40244017, 2025). "The pivotal role of GRK2 in regulating GPCRs in the context of cardiac function is well-established and GRK2 is a major therapeutic target for cardiac disease." (PMID 35386975, 2021). "As GRK2 has emerged as drug target in heart disease, we focus on its role in IAV infection and show that it is required for viral uncoating." (PMID 30206219, 2018). "Hence, GRK2 has emerged as promising drug target in heart disease and inhibitor development is under way53,54, which could eventually enable drug repurposing for the treatment of influenza virus infections." (PMID 30206219, 2018). "Among downstream signals of β-ARs, compelling evidence indicates that GRK2, GRK5, and Epac1 represent attractive therapeutic targets for cardiac disease." (PMID 33466800, 2021). "In this review, after a brief description of cardiac β-ARs, we discuss the pathophysiological roles of GRK2, GRK5, and Epac1 in cardiac disease." (PMID 33466800, 2021). "GRK2 and GRK5 are the prominent GRKs in the heart and elevated in heart disease." (PMID 35430346, 2022).
metabolic disease (8 papers, 2019 to 2026). A congenital disorder (due to inherited enzyme abnormality) or acquired (due to failure of a metabolically important organ) disorder resulting from an abnormal metabolic process. "In several pre-clinical models and in patients with cardiovascular and metabolic diseases, GRK2 expression and activity is enhanced leading to the disease progression and severity due to enhanced desensitization." (PMID 36275707, 2022). "As discussed in previous sections, diverse stimuli (catecholamines, angiotensin, high-fat diet) appear to converge in promoting enhanced GRK2 expression in different tissues and cell types in the context of given diverse cardiovascular and metabolic diseases." (PMID 30837878, 2019). "G protein-coupled receptor (GPCR) kinase 2 (GRK2), which phosphorylates agonist-occupied GPCRs to promote their desensitization, has been investigated as an attractive therapeutic target for cardiovascular and metabolic diseases." (PMID 36275707, 2022). "We summarize in this review the physiopathological roles of GRK2 in cardiovascular and metabolic diseases and focus on potential strategies to downregulate GRK2 functions based on our current knowledge about the structural features and mechanisms of regulation of this protein." (PMID 30837878, 2019). "GRK2 levels and activity are reportedly increased in different tissues of patients and/or in preclinical models in cardiovascular and metabolic disease-related contexts, contributing to disease progression by a variety of mechanisms, whereas GRK2 inhibition plays a protective role." (PMID 30837878, 2019). "GRK2 and GRK5 have already been proposed as potential drug targets in metabolic disease including T2D." (PMID 36030052, 2022).